BDNF (brain derived neurotrophic factor)
Diseases named in the same sentence as BDNF in open-access papers (continued):
Sharing a sentence is not in itself a finding about the gene and the disease.
neurodegenerative disease (continued). "BDNF is also being pursued in other neurodegenerative diseases." (PMID 40940730, 2025). "Neurodegenerative diseases and neuropsychiatric disorders may be related to insufficient neuronal supply of BDNF, and over the past 20 years, BDNF has been regarded as a key factor in the treatment of neuropsychiatric disorders." (PMID 40735218, 2025). "In addition, dysregulation of the proBDNF/BDNF axis is connected to the emergence of certain neurodegenerative diseases." (PMID 40380033, 2025). "Therefore, upregulation of the BDNF/CREB/ERK system induced by statins has been the focus of attention for the effective treatment of neurodegenerative diseases." (PMID 40358798, 2025). "As individuals age, BDNF levels decline, which may contribute to the onset and progression of various neurodegenerative diseases." (PMID 41318982, 2025). "Elevated levels of pro-inflammatory cytokines can lead to a decrease in BDNF expression, which may contribute to neurodegenerative diseases." (PMID 41304765, 2025). "Furthermore, evidence demonstrates that the Akt/cyclic adenosine monophosphate (cAMP) response element-binding protein (CREB) pathway, which induces the upregulation of BDNF, is a promising therapeutic target in neurodegenerative diseases including AD." (PMID 40005159, 2025). "Additionally, the therapeutic implications of increasing BDNF levels through physical exercise in patients with neurodegenerative diseases are highlighted, an area that remains underexplored." (PMID 39935805, 2024). "Additionally, BDNF improves cardiovascular and metabolic functions and is involved in preventing or delaying the development of neurodegenerative diseases." (PMID 39770947, 2024). "A better understanding of how exercise regimens affect BDNF regulation in these patients is needed, as neurodegenerative diseases could alter this response." (PMID 39935805, 2024). "The interaction between BDNF and TrkB improves neurogenesis, synaptic plasticity and neuroprotection and could be a therapeutic target against mental and neurodegenerative diseases." (PMID 38752280, 2024). "Consequently, various studies have investigated the therapeutic potency of BDNF in neurodegenerative diseases and especially in AD." (PMID 38971770, 2024). "Indeed, peripheral and central BDNF levels are reduced by the effects of chronic stress, aging and neurodegenerative diseases." (PMID 38006577, 2024). "Furthermore, once compounds stimulating the BDNF/TrkB pathway are validated, different mouse models of other neurodegenerative diseases can further evaluate these compounds." (PMID 39274839, 2024). "GDNF and BDNF could be useful for prospective studies involving the development of neurodegenerative diseases in IBD patients." (PMID 38891863, 2024). "Whether CBR subtypes upon activation increase BDNF in neurodegenerative diseases is not well understood; however, increased levels of BDNF have been reported in response to CB1R activation." (PMID 39796008, 2024). "As well, fingolimod improves neurological symptoms in many neurodegenerative diseases and attenuates the severity of the neurodevelopmental disorder Rett syndrome in a mouse model by increasing BDNF levels, thus regulating dendritic architecture and the morphology of hippocampal neurons." (PMID 39654365, 2024). "However, though provocative, therapeutic approaches using BDNF-induced improvements for neurodegenerative diseases in late adulthood have encountered many challenges in recent years." (PMID 39656488, 2024). "Reduction of PGN is in parallel with reduction of BDNF in different neurodegenerative diseases." (PMID 38006577, 2024). "However, derangement of BBB integrity in neurodegenerative diseases facilitates the transport of BDNF across the BBB into the brain." (PMID 38752280, 2024).
neurodegenerative disease (continued). "The neurotrophins BDNF and NGF are associated with the maturation, survival, and maintenance of neuron functions in the central nervous system (CNS), and their decrease gives rise to the development of neuronal injury and neurodegenerative diseases." (PMID 39628974, 2024). "Given its essential role in promoting neuronal survival and meditating synaptic plasticity in the motor system, BDNF might have an important impact on the pathophysiology of neurodegenerative diseases, such as PD." (PMID 39200225, 2024). "BDNF plays a crucial role in neuron survival, differentiation, and synaptic plasticity, influencing learning and memory abilities and has potential therapeutic effects on cognitive changes related to neurodegenerative diseases." (PMID 39221162, 2024). "Notably, many neurodegenerative diseases impair the production of BDNF in the brain; in turn, downregulation of BDNF exaggerates the neurodegenerative process." (PMID 38752280, 2024). "The levels of BDNF is also reduced in neurodegenerative diseases such as AD56." (PMID 38369574, 2024). "Panaxydol enhances the expression and secretion of nerve growth factor (NGF) and brain-derived neurotrophic factor (BDNF) in Schwann cells (SCs), improving SC viability and biological characteristics, effectively protecting neurons from degenerative disease damage." (PMID 39193331, 2024). "Notably, naturally derived phytoconstituents, including curcumin, cannabinoids, and genistein, reduce neurodegenerative diseases by increasing expression of BDNF." (PMID 38336772, 2024). "Noteworthy, ageing, chronic stress and neurodegenerative diseases inhibit the synthesis of BDNF." (PMID 38752280, 2024). "Indeed, the propagation of neurodegeneration in MS and other neurodegenerative diseases is related to the reduction of neuroprotective brain-derived neurotrophic factor (BDNF)." (PMID 38336772, 2024). "Furthermore, alterations in BDNF levels were found in neurodegenerative diseases, suggesting BDNF is a promising biomarker in most neurodegenerative conditions, which can be reliably measured in blood samples." (PMID 37686802, 2023). "BDNF and Nerve growth factor (NGF) might be appropriate prognostic and diagnostic markers of neurodegenerative diseases." (PMID 37841055, 2023). "DEC1 can bind to BDNF (Brain-derived neurotrophic factor) gene promoter 4 to negatively regulate BDNF transcription and alter neuronal excitability, which has important implications for regulating the development of neurodegenerative diseases." (PMID 37132111, 2023). "The inhibition of beta-estradiol may be related to the role of oestrogens in neurodegenerative diseases, which often overlaps with that observed for BDNF." (PMID 37958719, 2023). "Altogether, these studies position Npas4 and BDNF as outstanding therapeutic targets against AβOs-induced synaptotoxicity and may constitute targets to prevent the development of AD and other neurodegenerative diseases." (PMID 38001825, 2023). "BDNF level in brain and blood circulation is reduced in neurodegenerative diseases." (PMID 37396937, 2023). "BDNF levels are typically reduced in many neurodegenerative diseases and cognitive impairments." (PMID 38050515, 2023). "Exercise has been shown to have a positive effect on neurodegenerative diseases through the release of brain-derived neurotrophic factor (BDNF), the inhibition of neuronal cell death, and promotion of neurogenesis, collectively enhancing cognitive functions related to memory and learning." (PMID 38137233, 2023). "Thus, several approaches have been studied to evaluate the potential use of BDNF as biomarker in neurodegenerative diseases that require decision making in clinical practice." (PMID 37109038, 2023). "Similarly, downregulation of neuronal growth factors, such as brain-derived neurotrophic factor (BDNF), plays a key role in memory dysfunctions, and upregulation of these factors has shown promising rescuing effects against neurodegenerative diseases." (PMID 37372012, 2023).
neurodegenerative disease (continued). "Pro-BDNF maturation to BDNF, which happens via intracellular or extracellular proteases, is a delicate balance, which affects the modulation of cell survival or death and seems to be important in controlling BDNF activity in several pathological conditions, including neurodegenerative diseases." (PMID 35625004, 2022). "Since an adequate level of BDNF is necessary to prevent neurodegenerative disease, PC-EVs rich in BDNF might be used as a therapeutic strategy." (PMID 36231071, 2022). "The activation of BDNF/TrkB is required for neuron differentiation, survival, synaptic plasticity, and neurotransmitter regulation, while dysregulation of BDNF/TrkB contributes many pathological processes, including traumatic brain injury, brain ischemic injury, and neurodegenerative diseases." (PMID 35112804, 2022). "The curcuminoids also mitigate iNOS, COX-2, TGF-β1/2, matrix metalloproteinase-9 (MMP-9), and brain-derived neurotrophic factor (BDNF) expression, attenuate α-synuclein aggregation, and generally, lessen the severity of the symptoms of neurodegenerative diseases." (PMID 35883772, 2022). "However, further research is needed to weigh the benefits and the drawbacks of activating BDNF/TrkB signaling pathway in the management of neurodegenerative diseases." (PMID 35668928, 2022). "BDNF secreting cells are indicative for treating neurodegenerative diseases, especially for HD." (PMID 35626701, 2022). "Thus, there remains a great need for further exploration, especially of the targeting of modulate BDNF signaling for the treatment of aging-related neurodegenerative diseases, including Parkinson’s disease." (PMID 35743271, 2022). "Since then, research on BDNF in neurodegenerative diseases has grown tremendously." (PMID 35743271, 2022). "The activity of neuroprotective and pro-inflammatory factors, namely, brain-derived neurotrophic factor (BDNF), interleukin-6 (IL-6), and tumor necrosis factor-α (TNFα), involved in the neuronal cell damage in neurodegenerative diseases, were assayed in isolated hypothalamus." (PMID 35889920, 2022). "In addition, the therapeutic potential of BDNF in the treatment of neurodegenerative diseases will be reviewed." (PMID 35743271, 2022). "Relatedly, previous works showed that despite having adequate statistical power, BDNF did not predict different neurodegenerative disease diagnostic statuses." (PMID 34607976, 2021). "Brain-derived neurotrophic factor (BDNF) is a member of the nerve growth factor family which has been extensively studied for its roles in neural development, long-term memory, brain injury, and neurodegenerative diseases." (PMID 34695155, 2021). "This action has a crucial role for neuroplasticity and long-term potentiation, which are fundamental for learning and memory, and could account for the positive effect of BDNF in healthy population and neurodegenerative diseases." (PMID 33815257, 2021). "Abnormal increases in AGEs and Aβ1-42 induced by d-galactose can mediate inflammation, oxidative stress injury, mitochondrial dysfunction, and apoptosis and decrease BDNF and ACh levels, resulting in induction of the pathological processes of neurodegenerative diseases." (PMID 34336115, 2021). "BDNF level was also altered in many other neurodegenerative diseases and psychiatric disorders." (PMID 34607976, 2021). "Therefore, BDNF is a potential candidate for the treatment of neurodegenerative diseases, and especially for FA." (PMID 33670433, 2021). "However, not only BDNF/TrkB-mediated neuronal events, but also action of the proBDNF/p75 system (which is highly interactive and negatively regulates neural aspects) should be also considered as a major contributor in neurodegenerative diseases." (PMID 34071978, 2021).
neurodegenerative disease (continued). "In this review, we show the recent studies on possible contribution of BDNF-mediating intracellular signaling in neural function, and discuss finding concerning relationship between altered synaptic plasticity regulated by the BDNF and neurodegenerative diseases including AD." (PMID 34071978, 2021). "Additionally, BDNF has been found to have anti-apoptotic and anti-oxidant functions in experimental models of neurodegenerative disease." (PMID 34071762, 2021). "In addition to the estrogen-BDNF-NPY molecular cascade regulating estrogen-related neuroprotection in several neurodegenerative diseases, estrogen can also attenuate neuronal apoptosis by suppressing excessive calpain activation after SCI." (PMID 33390881, 2020). "So, exploiting this information, it can be analyzed whether ATF2 and hsa-miR-933 can play a neuroprotective role in neurodegenerative diseases by regulating their common target gene BDNF." (PMID 32993798, 2020). "Dysfunctions of BDNF and its associated signaling regulators such as TrkB, PI3K/Akt, Erk1/2 are intensively reported in the progress of neural atrophy and cell loss, which is the origin of neurodegenerative diseases." (PMID 32922183, 2020). "Altered BDNF functionality has been observed in different neurodegenerative diseases." (PMID 32188096, 2020). "Estrogen-BDNF interactions: implications for neurodegenerative diseases." (PMID 32876194, 2020). "The possibility of using exogenous BDNF as a therapeutic approach against neurodegenerative diseases has been hypothesized in recent years." (PMID 32397504, 2020). "Moreover, in neurodegenerative diseases, including PD, reduced neurotrophic support has been reported, such as brain derived neurotrophic factor (BDNF)." (PMID 32155131, 2020). "LA is used clinically to treat AD, but the growing knowledge we provide on glucose metabolism restoration by LA via the BDNF/TrkB/HIF-1α pathway in AD may support a novel therapy target for neurodegenerative diseases." (PMID 32973490, 2020). "It was found that the decrease in expression of NTs, especially BDNF observed in the aging process and in neurodegenerative diseases, may contribute to degeneration and death of neurons." (PMID 32050617, 2020). "In addition to neural plasticity, studies have clearly shown that BDNF plays an important role in a variety of nerve damages, and its reduction is closely related to a variety of neurodegenerative diseases." (PMID 32587661, 2020). "With compulsory roles in neurogenesis, synaptogenesis, neuronal repair and protection, alteration in BDNF dynamics may result in various neurological disorders and neurodegenerative diseases 3,4,5,6." (PMID 33173426, 2020). "A decreased level of BDNF has been observed in several neurodegenerative diseases." (PMID 32291635, 2020). "Thus, circulating BDNF has been proposed as a potential biomarker for neuropsychiatric disorders and neurodegenerative diseases." (PMID 32942585, 2020). "BDNF is a neurotrophin which plays an important role in synaptic plasticity, neuronal survival, differentiation and neuronal growth, and levels of BDNF decrease in neurodegenerative diseases." (PMID 32393193, 2020). "Several papers have claimed that small molecule TrkB activators could mimic BDNF in cellular assays and therefore be potentially useful in treating neurodegenerative diseases including AD 62-66." (PMID 32550908, 2020). "The role of neurotrophins such as the brain-derived neurotrophic factor (BDNF) in neuroregeneration has been reviewed, and many natural products that offer promise in neurodegenerative diseases also increase neuroregeneration by upregulating the expression level and/or activity of BDNF." (PMID 30999702, 2019). "Dysregulation of BDNF signaling is involved in several neurodegenerative diseases, including AD." (PMID 30733674, 2019).
neurodegenerative disease (continued). "Many studies have suggested that alterations in the levels of specific neurotrophic factors (NTFs), such as brain-derived neurotrophic factor (BDNF) and ciliary neurotrophic factor (CNTF), are associated with the pathogenesis of neurodegenerative diseases such as AD and Parkinson’s disease (PD)." (PMID 31766645, 2019). "A broader understanding of the factors that regulate altered neuronal activity and BDNF could help to identify new therapeutic targets in neurodegenerative diseases." (PMID 31456666, 2019). "Endogenous production of BDNF by voluntary exercise was shown in adult rats, and is purported to play a crucial role in neuroplastic effects of rehabilitation interventions of humans with neurodegenerative disease." (PMID 29568518, 2018). "The role of lithium in increasing activity of BDNF plus the role of BDNF in survival of neurons support the hypothesis that lithium might have a role to play in the treatment of neurodegenerative disease." (PMID 30618562, 2018). "Moreover, extensive experimental data indicate that BDNF plays an important role in the pathogenesis of neurodegenerative diseases." (PMID 30081596, 2018). "BDNF is a member of the neurotrophic family, which promotes neuronal survival, axonal growth, and neuroprotection, and has been recognized as a potential therapeutic agent for different neurodegenerative diseases." (PMID 30126083, 2018). "It is well known that BDNF and its high affinity receptor TrkB play essential roles to support survival in a variety of neuronal populations in the CNS and that they contribute to protect neurons against neurodegenerative disease, including AD." (PMID 30463271, 2018). "Since IL-1β accumulation is an invariant feature across many neurodegenerative diseases, our study suggest that compromised BDNF retrograde transport-dependent signaling may have important implications in neurodegenerative diseases." (PMID 28153028, 2017). "Taken together, the literature and our data suggest that IL-1β-induced impairment of BDNF-dependent Erk5 action may contribute to the deleterious role of inflammation in aging and neurodegenerative diseases." (PMID 28153028, 2017). "The role of lithium in increasing expression of BDNF plus the role of BDNF in survival of neurons has led to the suggestion that lithium might have a role to play in the treatment of neurodegenerative disease." (PMID 29127487, 2017). "Glucocorticoid resistance is a common feature of ageing, neurodegenerative diseases, and neuropsychiatric disorders, conditions that can be ameliorated with BDNF mimetic therapies (e.g., electroconvulsive shock, deep brain stimulation, antidepressant drugs, and exercise)." (PMID 26885402, 2016). "The expression of BDNF is influenced by many factors, and epigenetic regulation plays an important role in BDNF expression changes induced by environment contaminants and in neurodegenerative diseases." (PMID 26649298, 2015). "However, experimental preclinical studies show that BDNF has an important role in neurodegenerative diseases." (PMID 26667114, 2015). "BDNF also plays a crucial role in cognition, learning, and memory formation by modulating synaptic plasticity and is, therefore, a critical molecule in dementia and neurodegenerative diseases." (PMID 23651534, 2013). "Altered functionality of BDNF has been observed in different neurodegenerative diseases." (PMID 24024214, 2013). "Moreover, an increasing number of animal studies, as well as clinical studies, confirm the important role of the brain- derived neurotrophic factor (BDNF) in neurodegenerative diseases." (PMID 23924085, 2013). "Thus, NGF and BDNF, or their receptor agonists, have been used to treat AD and other neurodegenerative diseases." (PMID 23651534, 2013).